STAT1 (signal transducer and activator of transcription 1)
Diseases named in the same sentence as STAT1 in open-access papers (continued):
Sharing a sentence is not in itself a finding about the gene and the disease.
chronic mucocutaneous candidiasis (continued). "Inherited autosomal dominant gain-of-function (GOF) mutations of signal transducer and activator of transcription 1 (STAT1) cause a wide range of symptoms affecting multiple systems, including chronic mucocutaneous candidiasis (CMC), infections, and autoimmune disorders." (PMID 36105803, 2022). "This topical IVIG treatment reduced infection in 12 days at a rate of greater than 95 and 70%, respectively; the patient with the STAT1 mutation had had chronic mucocutaneous candidiasis since she was 8 months old and severe oral candidiasis resistant to voriconazole." (PMID 36713426, 2022). "In addition, three patients had familial chronic mucocutaneous candidiasis (CMC) due to pathogenic gain of function variants in STAT1." (PMID 35874679, 2022). "Counter intuitively, patients carrying dominant GOF mutations in STAT1 suffer from chronic mucocutaneous candidiasis (CMC), which results from an impaired T-cell-mediated IL-17 immunity." (PMID 39103360, 2024). "Signal transducer and activator of transcription 1 (STAT1) gain-of-function mutations are considered to be the cause of most hereditary chronic mucocutaneous candidiasis (CMC)." (PMID 39408156, 2024). "On the other hand, those with AD STAT1 gain-of-function (GOF) mutations present with chronic mucocutaneous candidiasis (CMC)." (PMID 39840042, 2024). "One of these disorders is the autosomal dominant form of chronic mucocutaneous candidiasis (CMC), which is defined by germ line STAT1 gain-of-function (GOF) pathogenic variants." (PMID 39114664, 2024). "For example, GOF mutations in the STAT1 gene cause Chronic mucocutaneous candidiasis (CMC)—a susceptibility to Candida infection of the skin, nails, and mucous membranes." (PMID 38037155, 2023). "The aim of this study was to characterize clinical effects and biomarkers in three patients with chronic mucocutaneous candidiasis (CMC) caused by gain-of-function (GOF) mutations in the STAT1 gene during treatment with Janus kinase (JAK) inhibitors." (PMID 36050429, 2023). "Hypermorphic mutations in signal transducer and activator of transcription 1 gene (STAT1 gain-of-function, STAT1 GOF) in humans cause an inborn error of immunity which is hallmarked by chronic mucocutaneous candidiasis (CMC)." (PMID 36172362, 2022). "Autosomal-dominant chronic mucocutaneous candidiasis (AD-CMC) is another CMC syndrome in which mutations in the coiled-coil domain of signal transducer and activator of transcription 1 (STAT1) have been identified as the underlying cause." (PMID 28080988, 2016). "Chronic mucocutaneous candidiasis (CMC) was found in 15 (32%) patients, linked to STAT1 and IL17RA mutations." (PMID 41209815, 2025). "STAT1 GOF mutations, associated with chronic mucocutaneous candidiasis and autoimmunity, are diagnosed via STAT1 gene sequencing and functional demonstration of exaggerated STAT1 phosphorylation in response to IFN-α or IFN-γ." (PMID 41438753, 2025). "Chronic mucocutaneous candidiasis (CMC) and hypothyroidism are common clinical manifestations of STAT1 GOF mutations." (PMID 40552831, 2025). "Over 98% of patients with STAT1 GOF develop chronic mucocutaneous candidiasis which can help differentiate the diagnosis from other autoimmune diseases." (PMID 37622085, 2023). "This led to a re-classification in two patients with Familial Chronic Mucocutanous Candidiasis (CMC), ID 45S and 46S, who both had a VUS in STAT1, which were reclassified to P and LP variants, respectively." (PMID 35874679, 2022). "Chronic mucocutaneous candidiasis (CMC) is the most common clinical symptom of singer transducer and signal transducer and activator of transcription 1 (STAT1) gain-of-function (GOF) mutations." (PMID 33413180, 2021). "Additionally, a STAT1-gain-of-function has been described to cause Th17 deficiency resulting in chronic mucocutaneous candidiasis (CMC)." (PMID 33147819, 2020).
chronic mucocutaneous candidiasis (continued). "Autosomal dominant (AD) signal transducer and activator of transcription 1 (STAT1) gain-of-function (GOF) mutations result in a primary immunodeficiency (PID) characterized by chronic mucocutaneous candidiasis (CMC), recidivating respiratory infections, autoimmunity, and vascular anomalies." (PMID 32582194, 2020). "Moreover, defects in intrinsic and innate immunity, including TLR-3 deficiency and chronic mucocutaneous candidiasis, were linked to pathogenic variants in TLR3 and STAT1, respectively, through autosomal inheritance." (PMID 40806973, 2025). "Conversely, 55.6% of STAT1 GOF mutations were within coiled-coil and DNA-binding domains, consistent with previous reports of GOF mutations within these domains in patients with chronic mucocutaneous candidiasis." (PMID 36669486, 2023). "A consistent immunophenotype in GOF STAT1 and HIES patients is impaired development of Th17 lymphocytes, which could be the reason for their susceptibility to chronic mucocutaneous candidiasis or invasive fungal infection." (PMID 36159645, 2022). "For instance, inherited genetic mutations in the Th17 pathway (e.g., STAT1, STAT3, STAT4) are known to lead to several diseases such as chronic mucocutaneous candidiasis (CMC), Hyper-IgE syndrome (HIES) and autoimmune polyendocrinopathy–candidiasis–ectodermal dystrophy (APECED)." (PMID 31972980, 2020). "Furthermore, heterozygous GOF mutations in STAT1 lead to chronic mucocutaneous candidiasis (CMC)." (PMID 31508401, 2019). "In addition, defects in trained immunity have been documented in patients with STAT1-mediated chronic mucocutaneous candidiasis (CMC) and following blockade of IFN-γ in PBMCs of healthy donors primed with C. albicans." (PMID 30304063, 2018). "The underlying pathophysiology driving chronic mucocutaneous candidiasis (CMC) in STAT1 gain-of-function (GOF) has been correlated to enhanced Th1 activity and decreased Th17 function." (PMID 36826612, 2023). "The clinical phenotype of STAT1 GOF is variable and includes autoimmunity, autoinflammation, and increased susceptibility to both chronic mucocutaneous candidiasis (CMC) and viral infections." (PMID 36189259, 2022). "STAT1 gain-of-function (GOF) is a primary immunodeficiency typically characterized by chronic mucocutaneous candidiasis (CMC), recurrent respiratory infections, and autoimmunity." (PMID 33679782, 2021). "Interestingly, impaired nuclear dephosphorylation also has been reported for AD, gain-of-function, STAT1 CCD mutants that are associated with chronic mucocutaneous candidiasis (MIM 614162), but none were reported as defective in nuclear localization." (PMID 29844444, 2018). "Autosomal-dominant (AD) gain-of-function (GOF) variants in STAT1 result in chronic mucocutaneous candidiasis (CMC), while AD STAT1 deficiency that impairs type II IFN-induced STAT1-mediated signaling could lead to isolated MSMD." (PMID 40491431, 2025). "In two adult STAT1-GOF patients, the JAKinib treatment ameliorated chronic mucocutaneous candidiasis and lymphopenia." (PMID 38578354, 2024). "JAK inhibitors may be effective in controlling chronic mucocutaneous candidiasis, the hyperactivation of the interferon response, that contributes to autoimmunity and autoinflammation, lymphopenia and severe viral and opportunistic infections in STAT1-GOF patients." (PMID 38578354, 2024). "For example, chronic mucocutaneous candidiasis (CMC) was present in 98% of patients with gain of function (GOF) mutations in STAT1 in one study of 274 individuals, and the few that did not have CMC, had invasive fungal or bacterial infections." (PMID 35663932, 2022). "STAT1 gain-of-function (GOF) mutations cause an inborn error of immunity with diverse phenotype ranging from chronic mucocutaneous candidiasis (CMC) to various non-infectious manifestations, the most precarious of which are autoimmunity and vascular complications." (PMID 37358695, 2023).
chronic mucocutaneous candidiasis (continued). "STAT1 gain-of-function (GOF) immunodeficiency typically presents with chronic mucocutaneous candidiasis (CMC), with or without a combination of bacterial, viral or mycobacterial infections, along with other complications including bronchiectasis, autoimmunity and vascular abnormalities." (PMID 36722341, 2023).
colorectal cancer (85 papers, 2013 to 2026). A primary or metastatic malignant neoplasm that affects the colon or rectum. "A reduction in STAT1 expression and/or a loss of its activation occurs in malignant colorectal cancer cells." (PMID 34299314, 2021). "To determine the role of STAT1 in colitis-associated colorectal cancer (CAC), we analyzed the tumor development and kinetics of cell recruitment in wild-type WT or STAT1−/− mice treated with azoxymethane (AOM) and dextran sodium sulfate (DSS)." (PMID 30235866, 2018). "We investigated sex‐specific STAT1 functions in colitis and colitis‐associated colorectal cancer (CRC) using mice with specific STAT1 deletion in intestinal epithelial cells (STAT1∆IEC)." (PMID 29419930, 2018). "KRAS mutations in colorectal cancer cells are related to inactivation of STAT1 and decreased sensibility of tumor cells to the anti-tumorigenic effects of IFN-γ." (PMID 30235866, 2018). "Colons from SOCS1 deficient mice exhibited hyperactivation of STAT1, accompanied with an increased in carcinogenesis-related enzymes, cyclooxygenase-2, and inducible nitric oxide and showed spontaneous development of colorectal carcinomas." (PMID 30235866, 2018). "P4HA2 may affect the STAT1/PD-L1 pathway to promote the development and inhibit antitumor immunity of colorectal cancer by binding to and downregulating the expression of STAT1, which may reveal a new pathogenic mechanism." (PMID 40406250, 2025). "Notably, high expression of STAT1 in colorectal cancer has been associated with a favorable prognosis." (PMID 38579174, 2024). "Interestingly, high IFNγ expression correlated with high STAT1 or CD274 expression in colorectal cancer, but high CBX3 expression was significantly associated with low expression levels of STAT1 or CD274." (PMID 38684864, 2024). "Because better subtyping of early stage colorectal cancer is particularly crucial for risk-stratifying patients prior to treatment, we examined whether STAT1 protein expression had prognostic value in early stage disease (stages I and II)." (PMID 32275681, 2020). "Our study also suggests that STAT1 could be added to the routine diagnostic mismatch repair markers to further differentiate the MSI subtype of early stage colorectal cancer." (PMID 32275681, 2020). "Our findings suggest that STAT1 may be used as a potential prognostic protein marker for stratifying the outcome risk of early stage MSI colorectal cancer." (PMID 32275681, 2020). "STAT1 is transcription factor complex that is involved in pro-apoptotic and anti-proliferative signaling pathways, and has been implicated in numerous cancers including colorectal cancer." (PMID 24324931, 2013). "Thus, STAT1 protein expression may be used as a potential risk-stratifying prognostic marker for early stage colorectal cancer, possibly guiding a decision for or against neoadjuvant therapy in stage I/II patients." (PMID 32275681, 2020). "Western blot analysis confirmed the increased expression of IFN-β and CXCL10 as well as phosphorylation of TBK1, IRFs, and STAT1 in FGFR4-overexpressing colorectal cancer cells." (PMID 40447617, 2025). "In pancreatic and colorectal cancer cells, the expression of Duox2 is regulated by the transcription factor STAT1." (PMID 40909948, 2025). "A study involving the tumor cell line HCT116 (human colorectal cancer) has shown that CD47 regulation is influenced by IFN-γ through the action of STAT1-mediated IRF-1, leading to an upregulation of CD47 expression in tumor cells." (PMID 40909948, 2025). "At present, studies have attempted targeted intervention with STAT1 inhibitors and have shown positive tumor suppressor effects in a variety of solid tumors such as glioblastoma, squamous cell carcinoma, and colorectal cancer." (PMID 40948762, 2025). "Future research should investigate the relationship between CD47 and PD-L1 expression and the activation of the IFN-γ/STAT1 pathway in colorectal cancer radiotherapy." (PMID 40909948, 2025).
colorectal cancer (continued). "Our further clinical analysis revealed also the antagonist effect between IFNγ and CBX3 in colorectal cancer on STAT1/PD-L1 expression." (PMID 38684864, 2024). "Given the important role of IFNγ/STAT1/PD-L1 axis in oncogenesis and cancer treatment, targeting the IFNγ signaling pathway as therapy is a rational and novel management in colorectal cancer." (PMID 38684864, 2024). "For example, STAT1 transcriptionally suppresses miR-181a expression to restrain colorectal cancer cell growth." (PMID 38764020, 2024). "Previous studies have reported the association between STAT1 and CXCL10 in PDAC and colorectal cancer." (PMID 37156839, 2023). "The allele G was previously associated with reduced apoptosis of colorectal cancer cells because it affects the coupled binding of transcription factors SP1 and STAT1 to chromatin, altering complex recruitment for transcriptional activation." (PMID 37798436, 2023). "Previous studies have shown that the AJUBA protein promotes colorectal cancer cell growth by suppressing the JAK1/STAT1/IFIT2 network and activating N-cadherin expression through interaction with Twist in colorectal cancer cells." (PMID 37765273, 2023). "For example, the LIM protein AJUBA promotes the growth of colorectal cancer cells via suppression of the JAK1/STAT1/IFIT2 network and activates N-cadherin expression through interaction with Twist in colorectal cancer cells." (PMID 35898403, 2022). "In several types of cancers, including colorectal carcinoma, pancreatic cancer, soft tissue sarcoma and metastatic melanoma, STAT1 expression has been correlated with cell cycle inhibition and sensitization to apoptotic stimuli." (PMID 36127323, 2022). "In colorectal cancer, L1CAM caused upregulation of clusterin expression in cancer cells as a result of the transactivating effect of STAT1 on clusterin." (PMID 35003395, 2021). "Here, we found that signal transducer and activator of transcription 1 (STAT1) was highly expressed in colorectal cancer (CRC) xenograft mouse models that were resistant to alisertib, an Aurora-A inhibitor." (PMID 34522170, 2021). "Even though STAT1 is a potential prognosis marker for colorectal cancer, the reports to date are variable." (PMID 34299314, 2021). "In support of this result, IDO1 expression in Paneth cells has been observed to be strictly regulated by STAT1 and regarded as an immunosurveillance escape strategy of colorectal cancer." (PMID 34946170, 2021). "NMI promotes cell proliferation through TGFbeta/Smad pathway by upregulating STAT1 in colorectal cancer." (PMID 33839701, 2021). "Recently, a correlation has been reported between shorter patient survival times and the high protein expression of STAT1 in early stage colorectal cancer." (PMID 34299314, 2021). "Previous studies have highlighted that IFNG up-regulates PDL1in a STAT1 dependent manner in gastric and colorectal cancer." (PMID 34566988, 2021). "In colorectal carcinoma, hepatocellular carcinoma, and pancreatic cancer, STAT1 acts as a tumor suppressor." (PMID 34276757, 2021). "Results generated from most STAT1 studies support the concept of STAT1 as a tumor suppressor in various cancers including colorectal cancer, which fulfills an opposite role to that of STAT3." (PMID 32422984, 2020). "Correlation of STAT1 expression with better prognosis has been reported for several cancers, including colorectal cancer, esophageal cancer, pancreatic cancer, hepatocellular carcinoma, soft tissue sarcoma, and metastatic melanomas." (PMID 32275681, 2020). "Our results revealed that high protein expression of STAT1 in early stage colorectal cancer, particularly of the MSI subtype, is positively correlated with shorter patient survival times, both the overall survival and disease-free survival times." (PMID 32275681, 2020). "These statistical analyses further support that high expression of STAT1 is a prognostic marker for poor survival in early stage colorectal cancer of the MSI subtype." (PMID 32275681, 2020).